CAT (catalase)
Diseases named in the same sentence as CAT in open-access papers (continued):
Sharing a sentence is not in itself a finding about the gene and the disease.
Hyperglycemia (continued). "Given that TRX and Catalase are strong antioxidant enzymes, higher expressions of them may in turn reduce the hyperglycemia-related lens oxidative stress injury in diabetic rats." (PMID 26759189, 2016). "Hyperglycemia determines an imbalance in the consumption of antioxidant enzymes, which are predominantly represented by the enzymes superoxide dismutase, glutathione peroxidase, and catalase." (PMID 27812607, 2016). "The increase in catalase activity in the diabetic group was in line with the results of Qujeq and Rezvani who argued that the increase in catalase activity in diabetic rats was due to the uncontrolled ROS production as a consequence of hyperglycemia which upregulated the expression of catalase." (PMID 27403200, 2016). "Hyperglycemia causes an increased production of free radical which plays a major role in the disruption of the cellular functions of the kidney that correlates to a decline in the endogenous ROS scavengers such as GSH-px, SOD, GST and catalase." (PMID 24223616, 2013). "The profound control of AuNPs over the anti oxidant enzymes such as GSH, SOD, Catalase and GPx in diabetic mice to normal, by inhibition of lipid peroxidation and ROS generation during hyperglycemia evidence their anti-oxidant effect during hyperglycemia." (PMID 20630072, 2010). "Hyperglycemia observed after 3 days of alloxan treatment, associated with a depression of glutathione (GSH) concentration, superoxide dismutase (SOD) and catalase (CAT) activities in the pylorus and ileum (P<0.001)." (PMID 21593966, 2008). "In addition, increased SOD and CAT enzyme expression with hyperglycemia have been demonstrated." (PMID 35434481, 2022). "The decreased level of catalase in the untreated diabetic rats might be as a result of inhibition of the enzyme by high level of superoxide or glycation of the hemprotein as a result of hyperglycemia." (PMID 31363395, 2019). "This resulted in overweight, accumulation of abdominal and liver fat, hyperlipidemia, and hyperglycemia, in addition to disturbances of transaminases and hepatic antioxidant enzymes (SOD and CAT)." (PMID 40278363, 2025). "Severe hyperglycemia in our STZ-diabetic rats also led to systemic oxidative stress, as evidenced by elevated ovarian MDA (malondialdehyde) and depleted GSH, SOD, CAT, GPx consistent with oxidative damage." (PMID 41300451, 2025). "Polypeptide-p and other bitter melon components reduce the generation of ROS by lowering hyperglycemia, which indirectly improves SOD and CAT activity and preserves GSH." (PMID 40184394, 2025). "In this study, hyperglycemia and sucrose consumption increased total antioxidant capacity and SOD activity, with minimal changes in catalase activity and a reduction in Glutathione Reductase activity." (PMID 40724491, 2025). "HF-HFr-STZ-induced hyperglycemia leads to the suppression of antioxidant activities of SOD, CAT, GPx, and GSH by showing high percent inhibition of these enzymes." (PMID 36401276, 2022). "In this study, the decrease in antioxidant potential due to hyperglycemia in STZ-induced diabetic rats was improved by the administration of the MR extract, with the marked restoration of the SOD and CAT levels." (PMID 35956936, 2022). "SIL promotes the expression of SIRT1, FoxO1, CAT, GPX1 and SOD2 of hyperglycemia Intervention of MC3T3-E1 by reducing intracellular ROS levels and restoring the activity and function of MC3T3-E1, similar to those from some researches." (PMID 36057883, 2022). "The current result is in agreement with our previous study, in which hyperglycemia increased MDA and decreased SOD and CAT." (PMID 36474578, 2022). "Furthermore, the GOx/CAT cascade reaction producing consecutive fluxes of oxygen spatially targets the neutral wound tissue, and accelerates the proliferation and remodeling phases of wound healing by addressing the issues of hyperglycemia, hypoxia, and excessive oxidative stress." (PMID 34983560, 2022).
Hyperglycemia (continued). "The effects of hyperglycemia on superoxide dismutase (SOD), catalase (CAT), glutathione peroxidase (Gpx), reduced glutathione (rGSH), nitric oxide, lipid peroxides, and protein carbonyl were investigated." (PMID 34986201, 2022). "In HFD/STZ-induced diabetic rats with hyperglycemia, naringin boosts antioxidant defense system activity-induced oxidative stress by lowering SOD, GSH, and catalase activity." (PMID 36556476, 2022). "Under diabetic condition, wound healing is impaired due to hyperglycemia induced excessive ROS derived from imbalanced antioxidant defense system including superoxide dismutase (SOD), catalase and glutathione peroxidases (GPx)." (PMID 29316680, 2018). "The diabetic rats exhibited significantly reduced pancreatic and hepatic catalase and GSH activities due to the recorded hyperglycemia and hyperlipidemia, which exhaust the activities of natural antioxidants and promotes free radicals formation." (PMID 29686746, 2018). "This study showed that the hyperglycemia induced kidney toxicity as indicated by significant decreases in SOD, CAT and GSH activities of diabetic rats by 53.41%, 97.91% and 82.75%, respectively." (PMID 28629341, 2017). "According to this, in muscle cells of diabetic animals the hyperglycemia increases SOD and catalase protein content." (PMID 27579154, 2016). "Additionally, in an in vivo model of streptozotocin‐induced hyperglycemia and diabetes type I in rats, CV showed beneficial effects on diabetic cardiomyopathy and increased protein expression of SOD2, SOD1, and catalase in heart and skeletal muscle." (PMID 39924769, 2025). "Under conditions of hyperglycemia-induced stress in in vitro models, these marine terpenoids show marked improvement in cell redox status due to increased activity of antioxidant enzymes, including SOD, catalase (CAT), and GPx." (PMID 40843204, 2025). "C3G intervention in animals significantly downregulates the level of ROS in the pancreas of diabetic db/db mice, upregulates the activities of superoxide dismutase (SOD) and catalase (CAT), alleviates the islet OS induced by hyperglycemia in diabetic mice, and ameliorates T2DM." (PMID 38348222, 2024). "Intervention with BPE (groups B, D, G) significantly improved the MDA and CAT levels in the diabetic mice, suggesting that BPE may counteract the oxidative stress induced by hyperglycemia, thereby strengthening the organism’s resistance to oxidative damage." (PMID 39765819, 2024). "Hyperglycemia mediated‐ROS production and cellular membrane lipid peroxidation concomitantly suppress cardiac endogenous antioxidant systems such as reduced GSH, SOD, and catalase and exacerbate myocardial damage." (PMID 35841183, 2023). "The hyperglycemia-increased glycation-increased free radical production triad may be responsible for the decrease in SOD, catalase, GPx, and rGSH levels in alloxan-diabetic rabbits." (PMID 34986201, 2022). "An INS reservoir (GOx, CAT, and BSA) and could counter hyperglycemia in diabetic rats over a 1-week period." (PMID 36246353, 2022). "Another reason behind the decreased activity of CAT and SOD might be the reduction of the protein expression levels that is a common phenomenon in hyperglycemia." (PMID 34222073, 2021). "Administration of a white tea extract to rats with hyperglycemia triggered a significant increase in SOD, CAT, GPX, and GSC-Px levels as well as a decrease in MDA levels in the liver and blood serum, which indicates stimulation of the synthesis of exogenous antioxidative enzymes." (PMID 34836227, 2021). "Also, neem attenuated hyperglycemia, and hyperlipidemia via induction of SOD, catalase (CAT) levels in diabetic rats." (PMID 33995939, 2021). "In addition, hyperglycemia attenuates anti-oxidative mechanisms through the glycation of scavenging enzymes, such as SOD and catalase." (PMID 31963869, 2020). "Hyperglycemia can increase H2O2 production and deregulate the expression of catalase." (PMID 31717560, 2019).
Hyperglycemia (continued). "Our finding is consistent with the data of other studies, in which the high sensitivity of catalase to nonenzymatic glycation was demonstrated, leading to a decrease in the activity of this enzyme with aging, hyperglycemia, and carbonyl-oxidative stress." (PMID 30254764, 2018). "The injection of polyethylene glycol-conjugated catalase (PEG-CAT), an H2O2 scavenger, may reverse hyperglycemia-induced tumor metastasis." (PMID 27433288, 2016). "This may be attributed to the fact that persistent hyperglycemia leads to increased H2O2 levels, which eventually results in the induction of CAT activity." (PMID 26439801, 2015). "Long-term hyperglycemia exerts the deleterious effects through overproduction of ROS that outweighs their degradation by antioxidant defense systems such as superoxide dismutase (SOD), catalase (CAT), heme oxygenase-1 (HO-1), and thioredoxin (Trx)." (PMID 25525607, 2014). "Hyperglycemia not only generates more reactive oxygen species (ROS), such as superoxide and hydrogen peroxide, but also attenuates the antioxidative mechnisms through the glycation of scavenging enzymes including SOD and catalase." (PMID 24250489, 2012). "A decrease in the activities of superoxide dismutase, catalase, and gluthatione peroxidase was observed under diabetic conditions, which may be explained by hyperglycemia-related non-enzymatic glycosylation leading to enzyme inhibition." (PMID 41226146, 2025). "On the one hand, high endogenous OS induced by stimuli, including hyperglycemia, hyperlipidemia, hypoxia, ERS and other stimuli; on the other hand, low expression of antioxidant enzymes such as superoxide dismutase (SOD), catalase (CAT) and glutathione peroxidase (GPx)." (PMID 39901210, 2025). "The reduction in glucose levels may have partially alleviated the inhibitory effect of hyperglycemia on autophagy, while the concurrent activation of Nrf2, increased antioxidant enzyme levels (SOD, CAT, GPx, GSH), and decreased MDA concentrations indicate the restoration of redox balance." (PMID 41300451, 2025). "An increasing bulk of studies proposes that hyperglycemia and high oxidants accumulation induced by free fatty acid (FFA) can more easily impair the function of β-cells due to antioxidant (SOD (Superoxide dismutase), CAT (Catalase), and GPx (Glutathione peroxidase)) subnormal expression in β-cells." (PMID 37520024, 2023). "In the present study, the significant lowering in GSH levels and CAT, total SOD and GPX activities, and the significantly increased MDA levels, as the marker of LPO, in various organs of diabetic rats approve the augmented oxidative stress induced by hyperglycemia." (PMID 32695286, 2020). "Previous studies have demonstrated that long standing hyperglycaemia leads to increased production of ROS, chronic oxidative stress and decrease in activity of endogenous antioxidant defense enzymes responsible for scavenging free radicals, such as SOD, CAT, and GPx." (PMID 33367177, 2020). "In addition, hyperglycaemia and dyslipidaemia perturbs renal antioxidant capacity by lowering glutathione (GSH), glutathione peroxidase-1 (GPx1), superoxide dismutase-1 (SOD1), and catalase (CAT) that subsequently induce lipid peroxidation, protein damage, and chronic inflammation." (PMID 38139208, 2023). "In addition to reducing hyperglycemia and/or excessive lipid storage, it could improve inflammation and oxidative stress at the cellular level by modulating the expression of cytokines and enzymes such as SOD, δ-aminolevulinic acid dehydratase, CAT, GST, GSH, GPx, and GRd." (PMID 37760813, 2023). "However, during the hyperglycemia, the SOD is unable to eliminate the excess ROS, which results in suppression of the antioxidant enzymes such as SOD1, SOD3, and catalase but not SOD2." (PMID 34326888, 2021).
breast carcinoma (125 papers, 2006 to 2026). "In the group of elderly women (aged 60–74 years), an association of the CAT gene polymorphism with the risk of developing luminal B subtype of breast cancer was found in a log-additive inheritance model (OR = 1.87; 95 % CI: 1.22–2.85; Padj = 0.0024)." (PMID 39027127, 2024). "Piperlongumine increases the intracellular ROS levels sufficiently to cause lethal oxidative stress in breast cancer cells by inhibiting the antioxidant enzymes CAT, Trx1, and Prx2." (PMID 39164783, 2024). "Overexpression of catalase was found to cause drug resistance in breast cancer cell lines in chemotherapy." (PMID 24454991, 2013). "Acatalasemic and hypocatalasemic mice, which have drastically decreased CAT levels in the blood and tissues, were more susceptible to mammary carcinoma than their wild type counterparts." (PMID 23153283, 2012). "Ahn J., Gammon M.D., Santella R.M., Gaudet M.M., Britton J.A.,Teitelbaum S.L., Terry M.B., Nowell S., Davis W., Garza C., NeugutA.I., Ambrosone C.B. Associations between breast cancer riskand the catalase genotype, fruit and vegetable consumption, andsupplement use." (PMID 39027127, 2024). "Interestingly, low CAT activity has been associated with an increased risk factor for many different cancers, including skin cancer, colorectal cancer, breast cancer, invasive cervical cancer, ovarian cancer, and prostate cancer." (PMID 31357514, 2019). "In breast cancer, the presence of the CAT SNP (rs1001179), was shown to confer increased risk." (PMID 26301412, 2015). "However, increased protein levels of catalase may induce resistance to this pro-oxidant association in breast cancer cells." (PMID 29467594, 2018). "We have shown that salivary catalase activity decreases more significantly in luminal breast cancer subtypes (Lum A, Lum B(−) and Lum B(+)), while AOA decreases to a greater extent in HER2-positive (Lum B(+) and Non-Lum) and TNBC." (PMID 41596237, 2026). "A decrease in salivary catalase activity was observed for all breast cancer phenotypes before surgery." (PMID 41596237, 2026). "In breast cancer patients, catalase activity in saliva decreased (−36.7%, p = 0.0017) while AOA increased (+37.0%) compared to the healthy control." (PMID 41596237, 2026). "Research has shown that oxidative stress markers, such as SOD and GPX, are significantly elevated in breast cancer patients, while catalase (CAT) activity is notably reduced." (PMID 39996878, 2025). "According to the literature, the level of catalase in oncological diseases, including breast cancer, decreases." (PMID 40429927, 2025). "Mitochondrial-targeted catalase has also been reported to preserve muscle contractile function in a breast cancer mouse model coupled with chemotherapy." (PMID 38594299, 2024). "In fibroadenomas and breast cancer, we recorded a reliable change in the following agents involved in oxidative processes: an increase in NO, peroxidase, DC, CAT, MDA and a decrease in SB, AOA." (PMID 39452912, 2024). "Consistent with our findings, silencing CAT expression in human breast cancer cells led to increased H2O2 production and enhanced cell proliferation." (PMID 39594482, 2024). "Parthenolide prevents the resistance of breast cancer cells to doxorubicin and mitoxantrone through the downregulation of Nrf2, CAT, and MnSOD." (PMID 39164783, 2024). "MDR analysis also showed a close interaction and mutual enhancement of effects between the APEX1 and SOD2 loci and the independence of the effects of these loci from the CAT locus in the formation of luminal B subtype breast cancer." (PMID 39027127, 2024). "It was observed that patients with breast cancer and benign breast illnesses have a lower CAT enzyme measurement." (PMID 37373429, 2023). "An independent study generated stably transfected derivatives of a breast carcinoma line in which tRNA-iMet-CAT expression was raised ~1.5-fold; this also stimulated proliferation significantly, as well as decreasing apoptosis." (PMID 37509247, 2023).
breast carcinoma (continued). "Compared with breast cancer cells, breast cancer stem cells (BCSCs) have a high ability to clear ROS and keep ROS at a relatively low level for the high expression levels of superoxide dismutase, catalase, and glutathione peroxidase." (PMID 36497050, 2022). "The findings suggested that oxidative stress and the development of hepatotoxicitymay promote breast cancer growth, presumably via catalase, TAS, MDA, NO, AST, and ALT activities." (PMID 37701507, 2022). "Nevertheless, our study showed a decrease in catalase activity in all groups of patients with breast cancer, reaching a minimum value in metastatic breast cancer." (PMID 35208240, 2022). "The antioxidative-enzyme-encoding genes paraoxonase 1 (PON1), glutathione-S-transferases (GSTs), and catalase (CAT) stood out in a retrospective series of 101 patients with HER2-positive breast cancer that received adjuvant trastuzumab." (PMID 36230587, 2022). "Treatment downregulating CAT has been shown efficacious to sensitize breast cancer cells to pro-oxidant therapy." (PMID 35370706, 2022). "Catalase activity in breast cancer patients was shown to be considerablylower after treatment than before treatment in our study." (PMID 37701507, 2022). "In the early stages of breast cancer (Groups I, and II), there was a minimum content of total protein and uric acid, a maximum content of urea and catalase activity." (PMID 35208240, 2022). "CAT inhibition has been associated with risk of many different cancers, while its overexpression (e.g., in MCF-7 mammary cancer cells) has been reported to result in a less aggressive phenotype cancer cells and an altered response to chemotherapy." (PMID 36552869, 2022). "In particular, high levels of oxidative stress in breast cancer have been reported in the literature since breast cancer cells also present an enhanced ROS production and low catalase activity." (PMID 34822465, 2021). "CAT is frequently down-regulated in tumors, e.g. Breast cancer was characterized by down-regulation of catalase and concomitant overexpression of SOD." (PMID 33515271, 2021). "The data indicated that catalase expression was lower in all three breast cancer cell lines versus fibroblast." (PMID 33669867, 2021). "Further studies are therefore needed to elucidate the role of catalase in the development of cardiotoxicity of breast cancer treatment after different treatment modalities." (PMID 33425072, 2020). "The presented results are consistent with literature data, indicating that catalase activity is induced in MCF-7 breast cancer cell line exposed to conjugated linoleic acid." (PMID 32397133, 2020). "A similar effect was reported for propolis and paclitaxel treatment, which increased the activities of enzymatic antioxidants SOD, CAT, and GPx in rats-treated compared with breast cancer-bearing animals treated with either paclitaxel or propolis alone." (PMID 32184916, 2020). "FSS-treated breast cancer cells isolated from stage III breast cancer patients showed an upregulation of antioxidant enzyme genes such as superoxide dismutase, catalase, and glutathione peroxidase, which potentially support cancer cell survival." (PMID 32708855, 2020). "Supporting evidence has been obtained using mimetics or genetic overexpression of SOD and catalase and antioxidant-based dietary supplements in breast cancer cell models and human studies." (PMID 30674338, 2019). "In an experimental metastasis model, where breast cancer cells were injected through the tail vein of immunocompromised mice, reduction in catalase levels resulted in a reduction in lung tumor burden." (PMID 30691108, 2019). "SODs and catalase have been considered biomarkers for the early detection of breast cancer based on the detection of fat peroxidation in breast cancer." (PMID 30674338, 2019). "On the other hand, overexpression of CAT in MCF-7 mammary cancer cells has been reported to result in a less aggressive phenotype and an altered response to chemotherapy." (PMID 31357514, 2019).